IL17RA (interleukin 17 receptor A)
Diseases named in the same sentence as IL17RA in open-access papers (continued):
Sharing a sentence is not in itself a finding about the gene and the disease.
autoimmune disease (continued). "The IL-17RA pathway may be activated by gut microbiota, and is related to most autoimmune diseases, such as rheumatoid arthritis, systemic lupus erythematosus, ankylosing spondylitis (AS), and inflammatory bowel disease." (PMID 34568080, 2021). "It is not clear what substances cause the activation of autoimmune disease and activate the IL-17RA pathway, or whether S. aeria is significantly increased during the onset of inflammatory bowel disease, rheumatoid arthritis, AS and other autoimmune diseases." (PMID 34568080, 2021). "Antibodies that neutralize IL-17A or its receptor (IL-17RA) deliver efficacy in autoimmune diseases, but no small-molecule IL-17A antagonists have yet progressed into clinical trials." (PMID 27527709, 2016).
asthma (26 papers, 2008 to 2025). "In conclusion, the studied IL17RA variants could be essential in asthma susceptibility and phenotype in children and adolescents." (PMID 38929236, 2024). "As no previous studies have uncovered the potential role of IL17 receptor A (RA) gene variants in asthma risk, we aimed to explore the association of four IL17RA SNPs (i.e., rs4819554A/G, rs879577C/T, rs41323645G/A, and rs4819555C/T) with asthma susceptibility/phenotype in our region." (PMID 38929236, 2024). "The protein IL-17RA is a target of the drug brodalumab, and the efficacy of this drug on asthma was tested in a phase 2 trial of 421 participants (brodalumab versus placebo; ClinicalTrials.gov: NCT01902290)." (PMID 36388766, 2022). "Among our genes that were driven by rare variants, i.e., ALOX15, CSF2RB, IL17RA, IL33, JAK2, S1PR4, and SH2B3, previous studies supported a rare variant association between IL33, which is a known asthma locus, and eosinophil count." (PMID 35935937, 2022). "Cyanidin, a natural small molecule, has been demonstrated to block IL-17RA and, thus, to inhibit IL-17A binding to its receptor and revealed therapeutic effects in a mouse model of experimental asthma." (PMID 35883573, 2022). "It is worth noticing that IL-17RA together with IL-17RB is an important part of IL-25 signaling—an epithelial derived alarmin significant in asthma pathobiology." (PMID 32842623, 2020). "Noteworthy, the number of TSLPR+, ST2+, and IL-17RA+ moDCs differed between asthma, COPD, and controls." (PMID 32842623, 2020). "Recent studies indicate a function for IL-17A/F and the IL-17 receptors IL-17RA and IL-17RC in models of experimental asthma." (PMID 32641167, 2020). "The sensor detected neutrophil-like dHL-60 cells that express IL-17RA and neutrophils from asthma patients, thus demonstrating a potential for diagnostics for IL-17RA-related diseases." (PMID 33266394, 2020). "In a previous study, plasma IL-25 concentrations, IL25 mRNA levels in bronchial brushings, and the expression of the IL-25 receptors IL-17RA and IL-17RB on eosinophils in subjects with severe asthma were observed to be significantly higher than those in normal subjects." (PMID 36674744, 2023). "Its receptor, constituted by IL-17RB and IL-17RA, is expressed by various cells contributing to asthma pathogenesis, such as T cells, ILCs, and inducible natural killer (iNKT) cells, as well as by structural cells including epithelial cells, fibroblasts, and endothelial cells." (PMID 35883573, 2022). "In addition to the protective effect of IL-17RA inhibition on asthma in males, our results further suggested reconsideration of efficacy of two protein-disease pairs." (PMID 36388766, 2022). "Importantly, the largest number of IL-17RA+moDCs was observed in asthma and COPD, suggesting the altered function of DC-IL-17A signaling in these diseases." (PMID 32842623, 2020). "The expression level of IL5RA in IL‐5‐activated eosinophils and the levels of IL17RA and CRTH2 in IL‐5 or IL‐17‐activated eosinophils were significantly higher for patients with asthma than for normal individuals." (PMID 39575691, 2024). "Because of the functional overlap between IL-17A and IL-17C and the corresponding receptor complexes IL-17RA/IL-17RC and IL-17RA/IL-17RE, we examined the function of IL-17RE in mouse models of OVA-induced experimental asthma and acute exacerbation thereof." (PMID 32641167, 2020). "The expression levels of IL17RA, IL4RA, integrin β2, CCR3, FCER1A, TGFB1, TLR‐3, TLR‐7, and TLR‐9 in eosinophils treated with IL‐17 for 3 h were higher for normal individuals than for patients with asthma." (PMID 39575691, 2024). "What’s more, the studies of brodalumab, a humanized monoclonal antibody that binds to IL-17RA, was stopped because of the relative lack of efficacy in the initial asthma clinical trial and a questionable safety issue." (PMID 38131042, 2023).
asthma (continued). "In conclusion, our study shows that children with STRA compared with younger controls without asthma have an exaggerated epithelial response to IL-17A, with increased expression of IL-17RA in the airway submucosa and epithelium." (PMID 27746241, 2017). "In contrast, our patients with STRA did show enhanced IL-17RA immunoreactivity in submucosa and epithelium as well as increased mRNA expression of IL-17RA and C on stimulation of PBECs with IL-17A when compared with controls without asthma." (PMID 27746241, 2017). "Furthermore, better symptom control, measured using the asthma control test (ACT), correlated with increased IL-17RA expression in the epithelial compartment in children with STRA." (PMID 27746241, 2017). "Blockade of IL-17RA with brodalumab, a human anti-IL-17RA monoclonal antibody, in subjects with inadequately controlled moderate-to-severe asthma taking regular inhaled corticosteroids did not have a significant impact on asthma." (PMID 28721208, 2017). "However, treatment with the humanised mAb brodalumab, which blocks IL-17RA, did not result in symptom improvement in patients with inadequately controlled moderate-to-severe asthma who continued their ICS." (PMID 41440490, 2025). "Although the protective effect of IL-17RA inhibition on asthma was relatively minor in the sex-combined trial (ClinicalTrials.gov: NCT01902290), our study suggested that the efficacy of this target on asthma in males may be worth reconsideration in future trials." (PMID 36388766, 2022). "As it has been shown that IL-17A and IL-17C both require IL-17RA for the induction of inflammatory mediators in target cells and IL-17C promotes Th17 cell responses we hypothesized that the specific IL-17C receptor IL-17RE has a function in OVA-induced experimental asthma." (PMID 32641167, 2020).
chronic mucocutaneous candidiasis (23 papers, 2012 to 2025). "In fact, it has been demonstrated that chronic mucocutaneous candidiasis (CMC) occurs in patients with autosomal recessive IL‐17RA deficiency and autosomal dominant IL‐17F deficiency." (PMID 39634792, 2024). "Mutations in IL-17RA and IL-17F have been linked to chronic mucocutaneous candidiasis disease and predisposition to Staphylococcus aureus infection." (PMID 37115755, 2023). "In fact, genetic deficiency of IL17RA or IL17F is associated with chronic mucocutaneous candidiasis and secukinumab -induced IL17F inhibition results in increased incidence of Candida spp." (PMID 34079536, 2021). "In man, rare recessive diseases associated with IL17RA include immunodeficiency 51 and chronic mucocutaneous candidiasis." (PMID 32448141, 2020). "The pathogenic variants associated with immunodeficiency 51 include missense variants as well as non-sense variants and lead to a total loss-of-function of IL17RA." (PMID 32448141, 2020). "The main infectious complication experienced is that of chronic mucocutaneous candidiasis, but in a study of 21 patients with inherited IL-17RA deficiency, 3 experienced recurrent lobar pneumonia." (PMID 29813133, 2018). "Autosomal recessive IL-17RA deficiency and autosomal dominant IL-17F deficiency also lead to chronic mucocutaneous candidiasis (CMC) with S. aureus dermatitis." (PMID 23383714, 2013). "In other forms of chronic mucocutaneous candidiasis disease, presenting with recurrent or persistent infections with Candida albicans, associations with either an autosomal recessive deficiency in the IL-17 receptor A (IL-17RA) or autosomal dominant deficiency in IL-17 F have been described." (PMID 23369364, 2012). "In humans, rare mutations in the genes encoding IL-17F, IL-17RA, IL-17RC, RORc and Act1 are strongly associated with chronic mucocutaneous candidiasis (CMC)." (PMID 26274976, 2015). "Autosomal recessive IL-17RA and autosomal dominant IL-17F deficiencies have been reported in chronic mucocutaneous candidiasis (CMC) patients." (PMID 24735832, 2014). "Chronic mucocutaneous candidiasis (CMC) was found in 15 (32%) patients, linked to STAT1 and IL17RA mutations." (PMID 41209815, 2025). "Chronic mucocutaneous candidiasis (CMC) is a recurrent infection of skin, mucosae and nails (onychomycosis), frequently seen in individuals with mutations that affect Th17 cells, the cytokines IL-17A and IL-17F, or their receptor IL-17RA." (PMID 25849644, 2015). "Thus, patients with autosomal recessive complete deficiencies in IL-17RA, IL17RC, or ACT1/TRAF3IP2 develop fully penetrant, severe, treatment-refractory mucosal infections by Candida species, termed chronic mucocutaneous candidiasis (CMC)." (PMID 34964702, 2022). "Variants in human IL17RA were reported to cause autosomal recessively inherited immunodeficiency 51 (OMIM 605461) and affected individuals show inborn susceptibility to several infections and especially to chronic mucocutaneous candidiasis." (PMID 32448141, 2020). "In humans, failure to generate effective Th17 responses (as a result of a range of mutations in, for example, IL-17RA, IL-17F, STAT1 genes) can result in chronic mucocutaneous candidiasis (CMC)." (PMID 26124761, 2015).
Arthritis (19 papers, 2009 to 2024). Inflammation of a joint. "We also used mice genetically deficient for AHR (Ahr KO) and IL-17Ra (Il17ra KO) to determine the in vivo mechanism of smoking-induced arthritis aggravation." (PMID 29884199, 2018). "Previously, we have shown that the primary antigen-induced arthritis (AIA) model is IL-23/IL-17 mediated, since IL-23p19- as well as IL-17RA-deficient mice were protected from progressive joint inflammation." (PMID 23469022, 2013). "In this study, we addressed the contribution of IL-17RA signaling to the effector phase of arthritis in the K/BxN serum transfer model by subjecting Il17ra−/− mice to serum transfer and found that IL-17RA deficiency attenuated the severity of serum-induced arthritis." (PMID 22028860, 2011). "Finally, since CD4+IFN-γ+ cells were lower in the inflamed joints of IL-23p19-deficient mice, we confirmed the importance of the IL-23/IL-17 axis using IL-17RA deficient mice showing a similar arthritis expression as IL-23p19KO mice." (PMID 20017902, 2009). "The results show that GMSC‐Exo has the same or stronger effects compared with GMSC in inhibiting IL‐17A and promoting IL‐10, reducing incidences and bone erosion of arthritis, via inhibiting IL‐17RA‐Act1‐TRAF6‐NF‐κB signal pathway." (PMID 34953015, 2022). "For example, aptamers blocking IL-17 binding to IL-17RA can relieve synovial destruction in animal arthritis models." (PMID 32486412, 2020). "This study shows that smoking-induced arthritis aggravation is dependent on AhR activation in Th17 cells and IL-17Ra signaling." (PMID 29884199, 2018). "The objective was to determine the variability in expression of IL-17A, IL-17F and their receptors IL-17RA and IL-17RC in the synovia of patients with arthritis." (PMID 25146432, 2014). "Conversely, inhibition of IL17 by antibodies against IL-17A or its receptor IL17RA protected against the development of arthritis." (PMID 23956763, 2013). "Accordingly, although arthritis in Il17ra−/− mice was attenuated in all phases, the more pronounced clinical difference was found in the second phase of arthritis when the arthritis is amplified and maintained by CXCR2 chemokine ligands." (PMID 22028860, 2011). "Instead, the presence of other pro-inflammatory cytokines, such as IL-1β, was sufficient to generate arthritis, leaving IL-17RA signaling as an amplifier of serum-induced arthritis rather than an absolutely required mediator." (PMID 22028860, 2011). "The notion that IL-17RA amplifies of arthritis is further supported by the observation that overexpression of IL-17A aggravates serum-induced arthritis." (PMID 22028860, 2011). "We found that IL-17RA contributes to the effector phase of arthritis through the direct induction of neutrophil-active chemokines, RANKL, and the matrix metalloprotease MMP3 in FLS." (PMID 22028860, 2011). "Nevertheless, these data suggest that the local induction of CXCR2 and CCR1 chemokines in the synovium is likely the major mechanism of the amplification of serum-induced arthritis by IL-17RA signaling." (PMID 22028860, 2011). "To determine the role of IL-17RA signaling in the effector phase of inflammatory arthritis, we analyzed the development of arthritis in Il17ra−/− mice compared to wild-type mice following the transfer of arthritogenic K/BxN serum transfer." (PMID 22028860, 2011). "In this study, we addressed the role of IL-17RA signaling in the effector phase of arthritis using the K/BxN serum transfer model and show that IL-17RA signaling reinforces destructive arthritis." (PMID 22028860, 2011). "In contrast, arthritis aggravation and changes in neutrophil infiltration were absent in IL-17RA-deficient mice." (PMID 39253090, 2024). "IL17RA is a key component required for IL17A activity, and blocking of IL17 binding by IL17RA could inhibit the expression of IL-6 to prevent synovial inflammation in arthritis." (PMID 34305456, 2021).
Arthritis (continued). "P. gingivalis induced periodontitis enhances the severity of articular injury during experimental arthritis; this aggravation of arthritis did not occur in IL-17RA-deficient mice." (PMID 31293577, 2019). "Our results suggest that IL-17RA signaling may amplify and sustain arthritis in this clinical situation." (PMID 22028860, 2011). "IL-17RA deficiency, however, did not completely abrogate arthritis." (PMID 22028860, 2011). "Our data now lend support to the notion that IL-17RA signaling may play a contributory role in multiple phases of human RA and thus should be considered as a promising pharmacological target for established arthritis." (PMID 22028860, 2011). "Thus, IL-17RA signaling appears to be involved in the effector phase of serum-induced arthritis." (PMID 22028860, 2011). "The results showed that GMSC‐Exo have the same or better effects in comparison with GMSC in reducing the incidence of arthritis and bone erosion in CIA mice by regulating the imbalance of Th17/Treg and inhibiting IL‐17RA‐Act1‐TRAF6‐NF‐κB signalling pathway." (PMID 34953015, 2022). "The absence of IL-17 signaling (Il17ra KO) conferred protection to smoking-induced arthritis aggravation." (PMID 29884199, 2018). "Similar to what was observed for AIA mice exposed to cigarette smoke, the AHR agonist FICZ failed to induce arthritis aggravation of AIA in Il17ra−/− mice." (PMID 29884199, 2018). "Using this model, we identified that smoking-induced arthritis aggravation is dependent on AHR activation in T cells, Th17 expansion, and interleukin 17 receptor A (IL-17RA) signaling, showing a strong link between this pollutant receptor and arthritis progression." (PMID 29884199, 2018). "Importantly, smoking-induced arthritis aggravation, determined by neutrophil infiltration in the joints and mechanical articular hyperalgesia in the AIA model, was absent in mice genetically deficient of IL-17RA (Il17ra−/−)." (PMID 29884199, 2018). "Furthermore, mice lacking IL-17RA develop a very mild form of experimental arthritis." (PMID 23956763, 2013).
psoriatic arthritis (18 papers, 2010 to 2025). Joint inflammation associated with psoriasis. "Although the IL-23/Th17 pro-inflammatory axis is closely linked to development of psoriasis, psoriatic arthritis and rheumatoid arthritis, a substantial role for IL-17A/F cytokine and IL-17RA in intestinal inflammation such as inflammatory bowel disease and Crohn ́s disease has been documented." (PMID 30304852, 2018). "Following our findings, IL17RA expression was also significantly higher in synoviocytes of RA and psoriatic arthritis (PsA) patients." (PMID 32650733, 2020).
Autoimmunity (17 papers, 2009 to 2025). The occurrence of an immune reaction against the organism's own cells or tissues. "IL-17RA is the receptor for IL-17A, a cytokine associated with autoimmunity and implicated in rodent models of ASD." (PMID 30483058, 2018). "Mounting evidence suggests that IL-17A causes pathology in autoimmunity, but little is known about mechanisms of IL-17RA signaling." (PMID 19400960, 2009). "Previous reports have shown that IL-17RA signaling helps promote B-cell activation and, importantly, germinal center formation and migration (53, –, 57) in the context of autoimmunity and bacterial infection." (PMID 41335125, 2025). "Therapeutic targeting of IL-17A and its receptor IL-17RA with antibodies has turned out to be a tremendous success in the treatment of several autoimmune conditions." (PMID 32174926, 2020). "IL-17A and IL-17F which are highly homologous members of the IL-17 protein family and bind the same receptor complex consisting of IL-17RA and IL-17RC were often described as pro-inflammatory cytokines with redundant role in inflammation and autoimmunity." (PMID 21858022, 2011). "In this regard, neutralizing antibodies against IL-17A and IL-17RA, which have been tested safe and effective for the treatment of autoimmunity in humans, may be tested as adjuvant therapies that accompany current cancer immunotherapies." (PMID 31775909, 2019). "Abs against IL-17/IL-17RA are in clinical trials for other autoimmune conditions." (PMID 27814401, 2016). "Hence, agents that inhibit the Th17 pathway at multiple points, including inhibitors of JAK kinases, IL-23, IL-17A and IL-17RA, are currently being used or evaluated in RA and other autoimmune conditions." (PMID 24513269, 2014). "To determine if increased IL-17 production contributes to the development of autoimmunity in Ets1 KO mice, we crossed Ets1 KO mice to mice lacking the IL-17 receptor A subunit (IL17RA KO) to generate double knockout (DKO) mice." (PMID 37691956, 2023).
inflammatory bowel disease (15 papers, 2018 to 2026). A spectrum of small and large bowel inflammatory diseases of unknown etiology. "The study of IL‐23R and IL‐17RA isoforms in periodontitis is important because it has been determined that some IL‐23R gene variants (G149R, R381Q, and V3621) are associated with protection in patients with inflammatory bowel disease, while other variants increase their susceptibility." (PMID 41536464, 2026). "Previous studies in patients with inflammatory bowel disease have found that strengthening the intestinal mucosal barrier function is closely related to the IL-17RA pathway." (PMID 40574858, 2025). "By integrating transcriptomic data from human inflammatory bowel disease (IBD) colonic biopsies with mouse dorsal root ganglion (DRG) single‐cell data, we identify IL‐17A and its receptor IL‐17RA as potential mediators of nociceptor activation." (PMID 40827457, 2025).